SLFN12L (schlafen family member 12 like)
Gene: Protein-coding gene on chromosome 17 (35,464,249 to 35,537,683, reverse strand). Ensembl gene ENSG00000205045.
Subcellular location: Membrane
Genetic constraint (gnomAD): Loss-of-function variants: 30 observed, 31.36 expected, observed/expected ratio (o/e) 0.96, 90% interval 0.71 to 1.3. The upper end of that interval is the gene's LOEUF score, 1.3, which puts it in group 5 of 6, group 1 being the genes least tolerant of losing a copy. Missense variants: 668 observed, 680.6 expected, observed/expected ratio (o/e) 0.98, 90% interval 0.92 to 1.05. Synonymous variants: 249 observed, 247.91 expected, observed/expected ratio (o/e) 1, 90% interval 0.9 to 1.12.
Homologues: Orthologues: chimpanzee SLFN12L (92% identical), macaque SLFN12L (92% identical), mouse Slfn4 (40% identical), mouse Slfn3 (39% identical), rat Slfn4l1 (38% identical), mouse Slfn2 (31% identical), rat Slfn2 (30% identical), mouse Slfn1 (26% identical), rat Slfn1 (25% identical). Paralogues in human: SLFN12 (71% identical), SLFN5 (41% identical), SLFN14 (39% identical), SLFN11 (36% identical), SLFN13 (36% identical), SLFNL1 (9% identical).
Diseases named in the same sentence as SLFN12L in open-access papers:
SLFN12L is named in the same sentence as 7 diseases in open-access papers, as found by Europe PMC text mining. Sharing a sentence is not in itself a finding about the gene and the disease. The quoted sentences say what the papers report.
gastric cancer (2 papers, 2020 to 2021). A primary or metastatic malignant neoplasm involving the stomach. "The potential role of SLFN12, which shares a very high degree of similarity with SLFN12L, awaits exploration in gastric cancer." (PMID 34571887, 2021). "In contrast to the apparent adverse roles of SLFN5 and SLFN12L in gastric cancer, analysis of gastric carcinomas from 169 patients suggested that high SLFN11 expression correlates with better survival, which improves when patients are treated with platinum-chemotherapy." (PMID 34571887, 2021). "SLFN12L+ myeloid cells express VEGF, IL-1β and TNF-α, which are known factors associated with MDSC regulation, an immunosuppressive cell of relevance to immunotherapy-resistant gastric cancer." (PMID 33348809, 2020).
Gastric Metaplasia (1 paper, 2024). Intestinal metaplasia of the gastric mucosa is an intermediate precancerous gastric lesion in the gastric cancer cascade from chronic gastritis and atrophy to dysplasia and adenocarcinoma. "Furthermore, the inhibition of SLFN12L has been shown to alleviate Helicobacter pylori (HP)-induced gastric metaplasia, suggesting potential support for clinical treatments where HP eradication is challenging." (PMID 39558948, 2024).
prostate carcinoma (1 paper, 2020). A carcinoma that arises from epithelial cells of the prostate gland. "Importantly, SLFN12L has been revealed to regulate intestinal epithelial differentiation and contribute to prostate cancer cell differentiation." (PMID 32669100, 2020).
sarcoidosis (1 paper, 2024). Sarcoidosis is a multisystemic disorder of unknown cause characterized by the formation of immune granulomas in involved organs. "Novel immune related genes and miRNAs including LYST, RGS14, SLFN12L, and hsa-miR-199b-5p, distinguished sarcoidosis from controls." (PMID 39080656, 2024). "Our integrated model revealed several novel genes and miRNAs between sarcoidosis and controls, including LYST, RGS14, SLFN12L, and hsa-miR-199b-5p." (PMID 39080656, 2024).
cancer (1 paper, 2022). A tumor composed of atypical neoplastic, often pleomorphic cells that invade other tissues. "The findings revealed that SLFN5, SLFN11, SLFN12, SLFN12L, SLFN13, and SLFN14 were expressed at higher levels in many cancers, including GC (stomach adenocarcinoma; STAD), while the SLFN14 expression levels were relatively low in all tumor and normal tissues." (PMID 36090985, 2022).
infection (1 paper, 2020). The state of being infected such as from the introduction of a foreign agent such as serum, vaccine, antigenic substance or organism. "For instance, we observed that the genes encoding interferon induced protein 44 (Ifi44 gene) and schlafen family member 12 like (Slfn12l gene) are two of the most highly induced genes in Muc1−/− mice vs. WT at 24 h post-infection." (PMID 32793510, 2020).
tumor (1 paper, 2022). "The results showed that the high SLFN5, SLFN11, SLFN12, SLFN12L, and SLFN13 expression in GC was positively correlated with lymph node metastasis, tumor stage, and tumor grade." (PMID 36090985, 2022). "Therefore, the study suggests that human SLFN, such as SLFN12L (a homologue of SLFN4), may serve as a biomarker for detecting human gastric mucosal pre-tumor transformation." (PMID 36090985, 2022). "The results demonstrated that SLFN5, SLFN11, SLFN12, SLFN12L, and SLFN13 expression in tumor tissues was significantly higher than that in normal tissues in paired, and unpaired tests, implying that they may play a role in promoting tumor progression in GC." (PMID 36090985, 2022).